SIRT1 (sirtuin 1)
Diseases named in the same sentence as SIRT1 in open-access papers (continued):
Sharing a sentence is not in itself a finding about the gene and the disease.
depression (continued). "In recent years, with the development of genome-wide association studies (GWAS), researchers have found that the SIRT1 gene rs12415800 locus significantly correlates with depression." (PMID 36177213, 2022). "Although we found that the SIRT1 gene rs12415800 single nucleotide polymorphism is associated with adolescent depression, it is impossible to conduct further mechanistic explorations." (PMID 36177213, 2022). "As proven by animal studies, chronic stress leads to reduced SIRT1 activity and elevated risk in terms of depression-like characteristics." (PMID 35664490, 2022). "In our study, both controls and patients with depression carrying the A allele of the SIRT1 gene rs12415800 exhibited more severe damage to the white matter structure of the adolescent brain." (PMID 36177213, 2022). "Kovanen's study of Finnish population aged 30 years and older also found SIRT1 Polymorphisms associated with depressive disorders." (PMID 36177213, 2022). "One of the first SNPs identified as related to depression by GWAS was located in the SIRT1 gene, which encodes a type III HDAC." (PMID 34276306, 2021). "SIRT1 is associated with the depression behavior in the mouse model and with depressive symptoms in schizophrenia patients." (PMID 33552387, 2021). "Libert and colleagues first reported that brain-specific SIRT1 knockout mice were resilient to depression, whereas mice with global SIRT1 overexpression were more susceptible to depression, based upon the forced swim and sucrose preference test results." (PMID 30705425, 2020). "SIRT1 is one of the first two genes linked to major depression, which has been revealed in both genders and different populations." (PMID 30705425, 2020). "Recent genome-wide association studies identified genetic variants of SIRT1 linked to major depressive disorders." (PMID 30705425, 2020). "The absence of a depressive phenotype in female mice was unexpected given that the genetic association between SIRT1 and major depression was first identified in a large population of female patients." (PMID 30705425, 2020). "The association between the SIRT1 gene and depression has also been suggested by other genetic analysis." (PMID 30705425, 2020). "This large-scale genome-wide association study identified two genetic variants that contribute to the risk of major depressive disorder, one of which is sirtuin 1 (SIRT1)." (PMID 30705425, 2020). "An independent study of Japanese subjects demonstrated a significant association between SIRT1 SNP and major depressive disorders." (PMID 30416425, 2018). "A genome-wide association study revealed that genetic variations near the Sirt1 gene are significantly linked to major depressive disorder (Converge consortium, 2015)." (PMID 30416425, 2018). "The most frequent SIRT1 allele frequencies in Russian population (Ò = 1024) and Depressive Disorder (DD) patients (N = 244)." (PMID 30662452, 2018). "Allele frequencies of the most frequent SIRT1 SNPs in general Russian population (N = 1024) and in Depressive Disorder (DD) patients (N = 244) in comparison with the “1000 genomes” study (data for European population)." (PMID 30662452, 2018). "The less frequent SIRT1 allele frequencies in Russian population (N = 1024) and Depressive Disorder (DD) patients (N = 244)." (PMID 30662452, 2018). "Among the seven types of SIRT family of proteins, an association between SIRT1 and depression has been found in several studies." (PMID 29163009, 2017). "Our findings indicate that downregulation of SIRT1 correlates in the long term with the susceptibility to experiencing depression following early-life adversities." (PMID 26327687, 2015). "We propose that SIRT1 is a developmental component of the response to childhood adversity that increases the susceptibility to depression." (PMID 26327687, 2015).
depression (continued). "Our investigation revealed that offspring that experienced maternal separation exhibited noticeable behaviors resembling anxiety and depression, which were linked to increased levels of hippocampal cytokines and reduced activity of the Sirt1 and activation of NF-kB." (PMID 41317200, 2025). "Therefore, the association between the SNP sites of the SIRT1 gene and depression in patients was explored." (PMID 39612426, 2024). "Moreover, Sirt1 activation in animal models of depression was associated with antidepressant effects." (PMID 38396638, 2024). "Brain ICAM-1, Sirt1 and NO are implicated in depression and are modulated by antidepressants." (PMID 38396638, 2024). "Additionally, SIRT3 works in conjunction with SIRT1 and is highlighted in studies of resveratrol and its effect on depression preclinically, particularly when associated with mitochondrial dysfunction." (PMID 39404407, 2024). "The level of Sirt1 expression is closely associated with anxiety and depression." (PMID 37273278, 2023). "For example, resveratrol can counteract anxiety- and depression-like behaviors induced by estrogen deficiency in adult female C57BL/6J mice by inhibiting pro-inflammatory processes in the hippocampus via the activation of the Sirt1/NF-κB signaling pathway." (PMID 37273278, 2023). "Recently, SIRT1 has been linked to major depressive disorder." (PMID 37507744, 2023). "Combined, these findings suggest that the pharmacological activation of Sirt1 may be a promising therapeutic strategy for inflammation-induced, depression-associated phenotypes." (PMID 37273278, 2023). "For example, the CONVERGE Consortium identified two genetic associations focusing on a sample of Chinese women with recurrent severe depression: two SNPs on chromosome 10 showed evidence of association, one near the SIRT1 gene and the other in an intron of LHPP." (PMID 36231907, 2022). "Together, these findings indicate that SIRT1 is highly susceptible to depression and may be a good therapy target." (PMID 35370858, 2022). "However, opposing findings have also been reported; in one study, mice with global SIRT1 overexpression had elevated anxiety and increased susceptibility to depression." (PMID 35370858, 2022). "Moreover, the CONVERGE consortium (CONVERGE consortium 2015) has linked the SIRT1 gene with major depressive disorder." (PMID 35554791, 2022). "CONVERGE team study showed that the OR value of A allele at rs12415800 site of SIRT1 gene in Chinese adult patients with recurrent depression was >1, suggesting that A allele may be a risk allele for depression." (PMID 36177213, 2022). "The NAD-dependent deacetylase SIRT1 has been linked to depression." (PMID 36552159, 2022). "Furthermore, our present study also showed that the improvement of the depression-like behaviors and the increased SIRT1 expression in SNI rats caused by lncRNA-84277 overexpression were reversed by miR-128-3p overexpression or SIRT1 knockdown." (PMID 35959106, 2022). "Moreover, it was displayed that the Sirt1 inhibitor EX527 or Sirt1 knocking down lentivirus (sh-Sirt1) in the hippocampus ameliorated CUMS-induced depression-like behaviors and the cognitive deficiency." (PMID 35401226, 2022). "SIRT1 has recently been linked to major depressive disorder." (PMID 35634375, 2022). "It was hypothesised that MD-B could be used to evaluate the connection between ̇OH and SIRT1, an acetylase enzyme associated with depression." (PMID 34163615, 2021). "Thus, in this short article, we review the association of SIRT1 and SIRT2 activity and depression, and evidence of the effects of SIRT1 and SIRT2 modulators on inflammation in vitro and depressive-like behaviours in vivo." (PMID 33669121, 2021). "Researchers demonstrated that chronic stress could increase the risk of depression-like behavior by reducing SIRT1 activity by establishing a mouse model of depression." (PMID 32849821, 2020).
depression (continued). "Our recent work provided evidence that suggests that the low plasma SIRT1 concentration might cause depression in patients with schizophrenia, which is also consistent with the results shown in the present study." (PMID 32849821, 2020). "Besides, SIRT1 overexpress mice were more susceptible to depression compared to their wildtype littermates." (PMID 33228716, 2020). "In this way, the adaptive loss of SIRT1/BK pathway and the concomitant loss of metabolic adaptation may contribute to the formation of depressive disorders under prolonged stress or repeated stressors." (PMID 30271963, 2018). "Recent evidence demonstrated an association between the Sirt1 gene and major depressive disorder." (PMID 27517628, 2016). "In addition, our study provides further support of the association between SIRT1 (rs3758391) and depressive disorders (major depressive disorder and dysthymia)." (PMID 26509718, 2015). "Using our model, we observed that ESI-induced stress is associated with a significant decline in SIRT1 protein and mRNA in the brain and peripheral blood mononuclear cells (PBMCs) in adulthood, when lower peripheral blood mRNA levels predict greater depression-like behavior." (PMID 26327687, 2015). "In addition, our study gave further support for the association of SIRT1 gene with depressive disorders (rs3758391) and diastolic blood pressure (rs2273773)." (PMID 26509718, 2015). "However, how Sirt-1 affected AD or depression is still unknown, especially the association among Sirt-1, AD, and depression." (PMID 33834065, 2021). "Animal experiments further indicate that upstream target genes of PGC-1α, such as AMP-activated protein kinase (AMPK) and SIRT1, are significantly decreased, thereby mediating the occurrence and development of depression." (PMID 40699781, 2025). "Isorhamnetin has the potential to be utilized as a treatment for anxiety and depression-like symptoms by adjusting pathways of neuroinflammation and the signaling axis of Sirt1 and NF-κB." (PMID 41317200, 2025). "Numerous studies have reported that SIRT1 takes part in the neuropathological conditions of mental disorders, including depression." (PMID 40237232, 2025). "Recent findings suggest that the activation of the Sirt1/NF-kB pathway by Polydatin, Sirt1 activator, can alleviate depression in mice by reducing inflammation in neurons." (PMID 41317200, 2025). "Given sex‐based differences in depression and the fact that SIRT1 is a sexually dimorphic gene in depression, future research should also investigate these impacts in female mice." (PMID 40237232, 2025). "A key focus has beenthe activation of the silent information regulator factor 2-related enzyme 1(SIRT1) signaling pathway, which emerges as a novel therapeutic target fortreating depression." (PMID 40071363, 2025). "This study confirmed that microglial SIRT1 mediates UB's antidepressant effects, positioning UB as a promising therapeutic candidate for depression by targeting neuroinflammatory pathways." (PMID 40237232, 2025). "Previous reports have shown that the SIRT1/FOXO1 axis contributes to hippocampal angiogenesis in depression treatment and facilitates wound healing in diabetic models." (PMID 40025506, 2025). "Overall, activation of the AMPK/SIRT1 signaling pathway holds great promise as a strategy to facilitate depression-like behavior." (PMID 39684318, 2024). "Systemic treatment with the SIRT1 inhibitor EX-527 also demonstrated efficacy at protection in rodent models of anxiety and depression." (PMID 39404407, 2024). "When resveratrol, a pharmacological activator of SIRT1, was directly infused bilaterally into the NAc, an increase in depression- and anxiety-like behaviors was observed." (PMID 39275174, 2024).
depression (continued). "It has been suggested that hippocampal SIRT1 signaling mediates anxiety- and depression-like behavior." (PMID 39744519, 2024). "We investigate the behavioral effects of SRT2104, a selective SIRT1 activator, and Resveratrol, one of the most potent natural SIRT1 activator, on anxiety- and depression-like behaviors in APP/PS1 mice." (PMID 39744519, 2024). "Pharmacological activation of SIRT1 also improves anxiety- and depression-like behaviors in APP/PS1 mice." (PMID 39744519, 2024). "In the patients with major depressive disorder, the blood expression of SIRT1 was lower than in the healthy controls or in those effectively treated." (PMID 39335541, 2024). "SIRT1 is a key target at the intersection of 20 (S)-Protopanaxadiol and depression and has good docking activity in molecular docking validation." (PMID 39519726, 2024). "Pharmacological activation of hippocampal SIRT1 function also reduced anxiety and depression-like behaviors in APP/PS1 mice." (PMID 39744519, 2024). "Conversely, selective depletion of SIRT1 in the NAc using viral-Cre in floxed SIRT1 mice resulted in decreased depression- and anxiety-like behaviors." (PMID 39275174, 2024). "Brain NO increased significantly (p < 0.05) in depression and anxiety and was associated with an ICAM-1 increase versus naive (p < 0.05) and a Sirt1 decrease (p < 0.05) versus naive." (PMID 38396638, 2024). "The study of intercellular adhesion molecule-1 (ICAM-1) and SIRT1, a member of the sirtuin family with nitric oxide (NO), is emerging in depression and anxiety." (PMID 38396638, 2024). "Chronic stress reduces SIRT1 activity in the dentate gyrus of the hippocampus, and pharmacologic and genetic inhibition of hippocampal SIRT1 function led to increased depression-like behaviors." (PMID 39275174, 2024). "Taken together, these results suggest that hippocampal SIRT1 mediates the ameliorative effect of exercise on anxiety- and depression-like behaviors in APP/PS1 mice through the PGC-1α/NRF1/TFAM/mitochondrial biogenesis pathway." (PMID 39744519, 2024). "Data showed that the expression of certain sites of the SIRT1 gene was related to the onset of depression." (PMID 39612426, 2024). "We found that pharmacological activation of SIRT1 also alleviates anxiety- and depression-like behaviors in APP/PS1 mice." (PMID 39744519, 2024). "Studies have shown that AMPK is involved in energy metabolism and the development of anxiety and depression-like behaviors through SIRT1." (PMID 39684318, 2024). "The SIRT1 gene can affect the occurrence of depression by regulating the activity of glucose metabolism and lipid metabolism pathways." (PMID 39612426, 2024). "The decrease of SIRT1 levels in PD patients leads to the enhancement of inflammatory reactions and oxidative stress, which promotes the occurrence of depression and anxiety." (PMID 37718350, 2024). "Across other regions of the brain, SIRT1 activation and overexpression hold promise for the improvement of depression and anhedonia." (PMID 39404407, 2024). "Collectively, these clinical research findings suggest a strong relationship between the onset of depression and the expression of the SIRT1 gene." (PMID 38448466, 2024). "In animal models of depression, treatment with resveratrol, a well-known SIRT1 activator, improved the excessive anxiety state and reduced depression-like behavior in Wistar–Kyoto (WKY) rats." (PMID 39684318, 2024). "In this study, male mice subjected to OVX surgery exhibited behavioral disturbances associated with depression, increased microglial activation, mRNA expression of NLRP3 and NF-κB, and decreased mRNA expression of sirtuin-1 in the hippocampus." (PMID 38306547, 2024). "Sustained social defeats in mice upregulate SIRT1 expression in the NAc, and modulating SIRT1 activity via pharmacological or genetic methods regulates anxiety- and depression-like behaviors." (PMID 38916735, 2024).
depression (continued). "Meanwhile, hippocampal SIRT1 signaling mediates the ameliorative effect of treadmill exercise on anxiety- and depression-like behavior in APP/PS1 mice." (PMID 39744519, 2024). "Within the medial prefrontal cortex, SIRT1 impacts depression-related behaviors through glutamatergic neurons in a sex-specific manner." (PMID 39404407, 2024). "At the same time, methods to improve activation of the AMPK and SIRT1 signaling pathways are also thought to enhance stress-induced depression-like behavior in animal models." (PMID 39684318, 2024). "Saffron, rich in phytochemicals—primarily crocin, a compound with strong potential for activating SIRT1—has demonstrated numerous other beneficial effects, including reducing anxiety and depression and improving sleep quality." (PMID 39770936, 2024). "A previous study reported that the plasma concentration of SIRT1 was positively correlated with BDNF levels in patients with depression." (PMID 38559694, 2024). "Pharmacological activation of SIRT1 function similarly reduces anxiety- and depression-like behaviors in APP/PS1 mice." (PMID 39744519, 2024). "Overall, our findings suggest that hippocampal SIRT1 signaling mediates the ameliorative effect of exercise on anxiety- and depression-like behaviors in APP/PS1 mice." (PMID 39744519, 2024). "A case study showed that 91 patients with depression and 85 healthy people were compared with SIRT1 mRNA levels in the blood to evaluate the differences between the 2 groups." (PMID 39612426, 2024). "It was aimed to explore the efficacy of luteolin in a mouse model of dry eye comorbid depression and its molecular mechanism via Sirt1/NF-κB/NLRP3 signaling pathway." (PMID 36641776, 2023). "In contrast, infusion of the SIRT1 antagonist, EX-527, into the NAc reduced the severity of depression in the mice." (PMID 37239191, 2023). "It has been demonstrated that the Sirt1 activity in mPFC pyramidal neurons plays a key role in the regulation of depression-related behaviors." (PMID 36641776, 2023). "Meanwhile, through our review of the literature, we learned that the SIRT1 inhibitor EX-527 attenuated depression-like behavior induced by CUMS stimulation." (PMID 36641776, 2023). "Hippocampal Sirt1 expression levels are reduced in sleep deprivation-induced pathological models, resulting in anxiety- and depression-like behavioral phenotypes in Wistar male rats." (PMID 37273278, 2023). "The mechanism of luteolin on depression-related dry eye disorder was assessed by the Sirt1 selective inhibitor EX-527." (PMID 36641776, 2023). "Exercise is an important means to improve energy metabolism and depression, but it remains to be established how SIRT1 acts during exercise and improves depression." (PMID 37239191, 2023). "To further elucidate the role of Sirt1 protein and dry eye-like symptoms in mice, we tested the tear secretion of mice in the dry eye and depression comorbidity group after the application of EX-527." (PMID 36641776, 2023). "This study implied that there are differences in the effect of SIRT1 in different brain regions on depression." (PMID 37239191, 2023). "The possible mechanisms of Sirt1 in depression include neurogenesis, glial activation, and neuroinflammation." (PMID 37124257, 2023). "To further investigate the in vivo role of Sirt1 signaling in the antidepressant mechanism of luteolin, we further investigated the mechanism of luteolin against depression-related dry eye disorder using the SIRT1 selective inhibitor EX-527." (PMID 36641776, 2023). "In conclusion, SIRT1 negatively regulates the expression of BDNF, CREB, SYN, and PSD95 through the SIRT1/miR-134 signaling pathway, promoting nerve regeneration and alleviating depression-like behavior." (PMID 37239191, 2023). "The results of this study suggested that maternal separation can lead to inflammation response and anxiety- and depression-like behavior in male offspring, effects that are mediated by the downregulation of the Sirt1/NF-κB signaling pathway." (PMID 37273278, 2023).